RRM1 (ribonucleotide reductase catalytic subunit M1)
Diseases named in the same sentence as RRM1 in open-access papers (continued):
Sharing a sentence is not in itself a finding about the gene and the disease.
cancer (continued). "However, the biological roles of RRM1 are not identical among these cancers." (PMID 23922955, 2013). "In contrast, although ATRi reduces RRM1 and RRM2 protein in cancer cells, it does not reduce dCK protein in cancer cell lines." (PMID 36130512, 2022).
adenocarcinoma (6 papers, 2013 to 2018). A common cancer characterized by the presence of malignant glandular cells. "EZH2 and RRM1 mRNA expression in resected stage I adenocarcinoma were associated with survival in a first validation set, but not replicated in a clinically and pathologically matched independent set." (PMID 30458017, 2018). "Adenocarcinoma-specific mRNA expression levels of EZH2 and RRM1 are associated with poor post-surgical survival in the first set of patients, but not replicated in a clinically and pathologically matched independent validation set." (PMID 30458017, 2018).
infection (3 papers, 2012 to 2023). The state of being infected such as from the introduction of a foreign agent such as serum, vaccine, antigenic substance or organism. "In contrast with that of mock-infection, the expression of RRM1 and RRM2 decreased 6 h after PHH cells were infected with HCV." (PMID 37513740, 2023). "In contrast with that of mock-infection, the expression of RRM1 and RRM2 decreased 6 h after Huh-7.5 cells were infected with HCV." (PMID 37513740, 2023). "The expression of RRM1 decreased at both 6 h and 72 h of PHH after infection with HCV, while the expression of RRM2 decreased at 6 hrs but increased at 72 h of PHH after infection with HCV." (PMID 37513740, 2023). "We started with the analysis of the expression pattern of TS, RRM1 and RRM2 (two subunits of RR) in SK-Mel-19 and SK-Mel-29 cells 6 days post-infection with control or MYC shRNAs, i.e. at the time point when the majority of MYC-depleted cells underwent senescence." (PMID 23249808, 2012).
renal disease (1 paper, 2015). "There was attenuation of association of SNPs near RRM1|STIM1 and STON2|SEL1L after adjustment (although still significant at p<0.05, unadjusted for multiple comparisons), suggesting that these SNPs have effects on SCDA levels mediated through these clinical factors, in particular renal disease." (PMID 26540294, 2015).
respiratory disease (1 paper, 2011). "A subset of genes co-expressed with AQP4 and associated to respiratory disease were assigned to potential anti-tumorigenic function like CAV1, EDNRB, or SELENBP1, whereas genes more related to pro-tumorigenic function like CDK2, FOXM1, PLK1 or RRM1 were found to be anti-correlated with AQP4." (PMID 21548930, 2011).
RRM1 also shares sentences with these, for which no sentence is quoted: colon tumors (5 papers); mesothelioma (3); Alzheimer disease (2); biliary tract cancer (2); colon cancer (2); hepatocellular carcinoma (2); lymph node metastasis (2); malignant pleural mesothelioma (2); proteinopathies (2); acute myeloid leukemia (1); adrenocortical cancer (1); benign tumors (1); Burkitt lymphoma (1); cholangiocarcinoma (1); Chronic Lymphocytic Leukemia (1); COVID-19 (1); endometriosis (1); endothelial dysfunction (1); Fanconi anemia (1); genital herpes (1); hematological cancer (1); Insulin resistance (1); large cell lung carcinoma (1); latent infection (1); leukopenia (1); malignant mesothelioma (1); myocardial infarction (1); nasopharyngeal carcinoma (1); neuroblastoma (1); neurodegenerative disease (1).
A further 12 diseases each share a sentence with RRM1 in 1 paper.